ALB (albumin)
Diseases named in the same sentence as ALB in open-access papers (continued):
Sharing a sentence is not in itself a finding about the gene and the disease.
diabetes (continued). "Multilevel mixed-effects models showed that greater age, male sex, diabetes, previous CVD, current or previous smoking, lower eGFR, lower serum albumin, and lower haemoglobin were independently associated with higher SAF in repeated measures over the follow-up period." (PMID 32658890, 2020). "After adjustment for patients’ age, body mass index, white blood cell count, the requirement of antibiotics during hospitalization, diabetes, RDW, and peak creatinine, serum albumin was independently associated with massive APE (OR 0.234, 95% CI 0.129–0.4242, P < 0.001)." (PMID 31936687, 2020). "Albumin, glucose, and creatinine are, for example, the key biomarkers for diabetes mellitus." (PMID 32260353, 2020). "In the univariate linear regression analysis, AoAC, CTR, diabetes mellitus, hypertension, diastolic blood pressure, fasting glucose, hemoglobin, baseline eGFR, calcium-phosphorous product, albumin, and log-formed UPCR were significantly correlated with eGFR slope." (PMID 30926946, 2019). "CQ1: Is the measurement of urine albumin recommended in a patient with diabetes mellitus?" (PMID 30506489, 2019). "Induction of diabetes mellitus caused a significant elevation of BGL, TG, TC, LDL cholesterol, HDL cholesterol, liver enzymes, serum creatinine and blood urea, and a significant decrease in the serum albumin, HDL, and the body weight." (PMID 32128099, 2019). "The best classification accuracy (64.30%) was achieved by using the following nine candidate variables: age, sex, serum creatinine level, serum albumin level, haemoglobin level, heart failure, diabetes mellitus, blood urea nitrogen level, and serum phosphorus level." (PMID 30971708, 2019). "In univariate analysis, AoAC, CTR, study group of AoAC ≥ 4 and CTR ≥ 50%, diabetes mellitus, hypertension, systolic blood pressure, fasting glucose, hemoglobin, baseline eGFR, calcium-phosphorous product, albumin, and log-formed UPCR were significantly correlated with rapid renal progression." (PMID 30926946, 2019). "The risk factors for developing an SSI are age, comorbidity (American Society of Anesthesiologists score ≥3), diabetes, malnutrition, low serum albumin, radiotherapy and steroid use, high body mass index, host immune status, smoking, site, and level of wound contamination." (PMID 31572804, 2019). "For example, five months of CML-modified albumin injection into healthy rats (eliciting similar circulating AGE levels observed in individuals with diabetes) resulted in a 50% increase in renal AGE content and histological features indicative of glomerulosclerosis." (PMID 30823632, 2019). "Our results showed that health depreciation factors, such as Charlson’s comorbidity index, diabetes and hyperlipidemia, significantly increased older adults’ frailty; in contrast, albumin and mini nutritional assessment significantly decreased older adults’ frailty." (PMID 31892225, 2019). "Age, diagnosis, staging, performance scale, metoprolol use, heart, renal diabetes, Chronic Obstructive Pulmonary disease, diabetes, operation type and length, carcinoma antigen 125, ascites, albumin, surgical procedure, hospitalization length, and complications were recorded." (PMID 31673467, 2019). "Besides the vascular access types, the overall mortality rates were significantly higher among elder, high high-sensitivity CRP (hsCRP), diabetes mellitus, lower albumin, and high AST/ALT patients." (PMID 31341241, 2019). "In addition, male sex (36.7% vs. 53.5%, P = 0.081), preoperative albumin (35.2 vs. 38.9 g/ml, P = 0.067), and diabetes (43.3% vs. 27.5%, P = 0.071) tended to correlate with AL." (PMID 31255181, 2019). "Univariate analysis showed that the clinical risk factors for PARE were male gender (p=0.04), diabetes (p=0.004), symptoms of pleuritis (pleuritic chest pain or anhelation) (p=0.003), WBC>10×109/L (p=0.001), Albumin level <2.5 g/dl (p=0.012), and positive sputum culture (p=0.026)." (PMID 30994710, 2019).
diabetes (continued). "Moreover, there were no statistical differences between the two groups with respect to gender, body-mass index, diabetes mellitus, hypertension, cardiovascular disease, preoperative albumin, operative site, or forced expiratory volume-one second (FEV1)." (PMID 31689308, 2019). "In the multivariate Cox proportional hazards analysis after adjusting for age, sex, albumin, diabetes, hypertension, and history of CVD, the adjusted HR values were 0.40 (95%CI 0.17–0.90, P = 0.027) for higher FTI and 0.28 (95%CI 0.09–0.76, P = 0.011) for higher SMI." (PMID 30759133, 2019). "They included the age, dialysis vintage, average ultrafiltration, Log (CACS + 1), warfarin use, serum potassium, hsCRP, phosphate, uric acid, iPTH, Mg < 2.4 mg/dl, serum albumin, gender (male), presence of diabetes mellitus, urine volume ≥ 100 ml/day, and Log FGF23 at baseline." (PMID 30977017, 2019). "Despite some limitations, urinary albumin level measurement remains the gold standard for diagnosing and categorizing DN because one of the first asymptomatic clinical manifestations of microvascular damage in diabetes is a change in UAE." (PMID 31569548, 2019). "Human serum albumin is one of most abundant plasma proteins and heavily glycated in diabetes." (PMID 32030095, 2019). "The clinical model included age, sex, ACEI/ARB usage and variables with p < 0.05 in univariate analysis, including diabetes mellitus, hypertension, diastolic blood pressures, fasting glucose, hemoglobin, albumin, baseline eGFR, calcium-phosphorous product and proteinuria (χ2 = 114.72)." (PMID 30926946, 2019). "The results showed that age, duration of diabetes, FPG, serum albumin and SBP were independently associated with DR, and that age, duration of diabetes, FPG, serum albumin, triglycerides, SBP, hypertension and white blood cell count were independently associated with DKD." (PMID 31427625, 2019). "In the same study, significant correlations of overhydration with markers of nutritional and inflammatory status (lower serum albumin and higher interleukin-6 and tumor necrosis factor-α) were reported in addition to those with systolic blood pressure, cardiovascular diseases, and diabetes mellitus." (PMID 30894885, 2018). "Indirect factors are moisture, sensory perception, diabetes, low albumin and poor nutrition." (PMID 30537947, 2018). "They recorded reduction of the level of salivary globulin, due to limited filtration of immunoglobulins down into the saliva compared with increase serum albumin leakage into the saliva, suggesting the possibility of low grade sialadenitis as a complication of diabetes." (PMID 30304036, 2018). "However, SS treatment reversed diabetes-induced dyslipidemia and urinary albumin/creatinine ratio in db/db mice." (PMID 30223524, 2018). "We found increased risk of diabetes seen in CKD stage 3~5 using age- and sex-matched conditional logistic regression, adjusted for age, sex, Obesity, proteinuria, HCV, hypertension, CVD, dyslipidemia, hemoglobin, albumin, uric acid, ammonia and CTP class.." (PMID 29416767, 2018). "Additionally, subgroup analysis revealed that intensive retraining independently reduced the risk of the first episode of peritonitis in older subjects (age ≥60) after adjustments for sex, diabetes, academic year, centre size, haemoglobin and albumin level." (PMID 30150627, 2018). "A number of models have been developed and validated that predict the risk for the development and/or progression of CKD and DKD using readily available laboratory values, such as eGFR, urinary albumin excretion, and blood pressure, as well as age, sex, diabetes status, and ethnicity." (PMID 29457196, 2018). "Albumin may be oxidatively modified in vivo in chronic kidney disease (hemodialyzed patients), diabetes mellitus liver disease and other diseases." (PMID 29554100, 2018).
diabetes (continued). "Because age, duration of diabetes, BMI, and HbA1c were significantly related to urinary albumin, eGFR, and mortality, we performed Cox regression analyses adjusted for these confounding parameters, to evaluate the associations of albuminuria and eGFR reduction with all-cause mortality." (PMID 30142885, 2018). "However, urinary albumin levels are known to increase not only as a result of AKI, but also due to factors such as fever, exercise, dehydration, diabetes, and hypertension; thus, the specificity of urinary albumin as a biomarker of AKI is considered limited." (PMID 28856465, 2018). "Finally, urine albumin-to-creatinine ratio testing was performed in 50% of AI/AN aged ≥65 years with diabetes in 2013, increasing to 62% by 2016." (PMID 28081061, 2017). "Finally, the chronic nature of diabetes mellitus leads to poor nutrition and ultimately lower levels of serum albumin in these patients." (PMID 28326157, 2017). "Testing for urine albumin, which is an early marker of kidney disease, is recommended for all patients with diabetes, and treatment with angiotensin-converting enzyme inhibitors or angiotensin-receptor blockers is indicated for persons with diabetes and hypertension." (PMID 29095800, 2017). "Recent study has shown that some patients with diabetes have advanced renal pathological changes and progressive kidney function decline even if urinary albumin levels are in the normal range, indicating that albuminuria is not the perfect marker for the early detection of DKD." (PMID 28182086, 2017). "Similarly, among persons with diabetes aged ≥65 years, the rate of urine albumin-to-creatinine ratio testing is 55% higher in AI/AN compared with Medicare beneficiaries." (PMID 28081061, 2017). "Moreover, this study is the first to describe the influence of diabetes on the expression of hepatic markers (ALB, AFP), HNF-4α and miR-122 in NOD fetus liver." (PMID 28319104, 2017). "Lower pre-albumin was significantly associated with older age, higher tumor stage (muscle invasive vs nonmuscle invasive), higher rate of diabetes, regional lymph node metastasis and LVI (all p<0.05**), but not gender, tumor location and tumor grade." (PMID 27906675, 2017). "The albumin/creatinine ratio is a chronic kidney disease marker, and it is a well-validated marker of aging and disease processes because several common diseases, e.g. diabetes and hypertension, ultimately trigger kidney malfunction and failure." (PMID 28422991, 2017). "Also in the present series of patients with UTUC, those who had low pre-albumin level were more likely to have diabetes, higher T stage, N stage and lymphovascular invasion comparing with those with normal pre-albumin level." (PMID 27906675, 2017). "Patients with lower eGFR were older and tended to have a higher prevalence of diabetes, hypertension, chronic obstructive pulmonary disease, dyspnea at moderate exertion, and chronic heart failure, lower concentrations of serum albumin and hematocrit, and a lower prevalence of smoking history." (PMID 28747700, 2017). "Serial changes in serum albumin concentration were measured from baseline to one year before prediabetes diagnosis, and then from the time of prediabetes diagnosis to progression to overt diabetes or final follow-up." (PMID 28430803, 2017). "In Receiver operating characteristics (ROC) curve analysis showed the area under the ROC curve (AUC) for HbA1c was the largest among the variables, and it is significantly larger than those for serum albumin change in predicting both prediabetes (p < 0.001) and diabetes (p = 0.011) development." (PMID 28430803, 2017). "In the present study, we developed a new prognostic prediction model of composite CV events tailored for HD patients including HD-specific predictors such as age, diabetes mellitus status, history of CV events, dialysis time per session and phosphate and albumin levels." (PMID 28273175, 2017).
diabetes (continued). "In this study, age, diabetes, and levels of albumin were potential predictors of mortality." (PMID 28474577, 2017). "The decline of plasma proteins in diabetes, albumin and globulin, which are mainly synthesized by the liver, might be from the augmentation of protein catabolism or microproteinuria, indicators of diabetic nephropathy." (PMID 28662699, 2017). "Moreover, a marker of glomerular membrane permeability, urine albumin-to-creatinine ratio, remained unchanged 4 weeks after induction of diabetes." (PMID 28934365, 2017). "Also, increases in glomerular filtration rate and minor increases in urinary albumin excretion have been reported early in the course of diabetes." (PMID 28699988, 2017). "Under physiological conditions, circulating albumin carries approximately 0.1–2.0 moles of fatty acid per mole of protein; this number increases to about 6 during fasting or maximum exercise, or in patients with diabetes or cardiovascular disease." (PMID 28662200, 2017). "Between August 1988 and February 2013, 2648 diabetic patients aged ≥18 years underwent an initial diabetes scrutiny, were clinically diagnosed with type 2 diabetes and had a normal serum creatinine concentration and urinary albumin-creatinine ratio (ACR) <300 mg/gCr on repeated measurements." (PMID 27210499, 2016). "Importantly, in the context of diabetes, albumin synthesis is dependent on adequate insulin reserve." (PMID 27504458, 2016). "The results showed that plasma albumin level decreased in diabetic mice when compared to control group (P<0.05) and increased in diabetic BA 10 mg/kg (P<0.05), BA 20, 40 mg/kg (P<0.01) and metformin (P<0.001) treated mice versus to diabetes group." (PMID 27921024, 2016). "However, BPS treatment efficiently reduced plasma creatinine and 24 h urinary albumin, acting as a nephroprotective agent in diabetes." (PMID 27212945, 2016). "A Cox regression model was used to estimate the HR, so as to identify the factors, namely older age, preexisting diabetes, cardiovascular diseases, body mass index (BMI), initial albumin, and Δalbumin, could affect patient outcomes independently." (PMID 27015223, 2016). "The rate of degradation of albumin in obesity and diabetes may also influence the level of glycated albumin if changed." (PMID 27338619, 2016). "Age, diabetes, cardiovascular diseases, BMI, initial albumin, and Δalbumin could affect patient outcomes independently." (PMID 27015223, 2016). "Likewise, the predicted serum albumin levels of diatebes participants would be 0.08 g/dL lower than non-diabetes participants." (PMID 27542730, 2016). "Under the Japanese health insurance system, routine measurement of urine albumin is permitted for patients at high risk for cardiovascular disorders such as diabetes mellitus but not for other disorders." (PMID 27169575, 2016). "The high number of values exceeding the microalbuminuria threshold observed in this study could then more likely be due to other known factors affecting urine albumin excretion such as diabetes, hypertension, or intensive exercise." (PMID 27729976, 2016). "Our findings suggest that other diseases, such as cancer, heart disease, stroke, hypertension, diabetes, and liver disease, might also mediate the relation between serum albumin and socioeconomic status." (PMID 27276092, 2016). "In this study, our model showed that serum bicarbonate concentrations less than 22 mmol/L were significantly influenced by urine volume, serum albumin and dialysis vintage, adjusting forage, sex, diabetes mellitus, nPCR as a marker of catabolism and hsCRP as a marker of inflammation." (PMID 28933414, 2016). "When age, hemoglobin, phosphorus, albumin, potassium, 24-h urine volume, SGA, and diabetes were adjusted in stepwise multivariate analysis, the risk of death among elderly PD patients was 2.99 times higher than that in the younger PD group with a statistically significant difference (P = 0.009)." (PMID 26121574, 2015).
diabetes (continued). "On the other hand, albumin excretion may be increased in response to pathological or physiological processes unrelated to diabetes such as posture, exercise, puberty, smoking, obesity, and infection." (PMID 26270544, 2015). "On univariate logistic regression analysis at baseline, elevated cFLC was associated with age, gender, diabetes, previous cardiovascular event, hypertension, smoking, eGFR, uACR, hsCRP, PWV, serum albumin, Hb, WBC, total protein, bicarbonate, cholesterol, HDL, and uric acid." (PMID 26132658, 2015). "We examined the frequency of elevated urine albumin concentration (UAC) and its association with metabolic syndrome (MetS) and metabolic markers in 515 nondiabetic Mexican adolescents stratified by family history of diabetes (FHD)." (PMID 26347891, 2015). "Given that BNP and atrial natriuretic peptide bind to the same receptor and have the same biological activity, the elevated levels of BNP cause an increase in the glomerular hydraulic pressure and ultimately induce albumin excretion in patients with diabetes mellitus." (PMID 26473035, 2015). "In the absence of consistent and ample clinical data supporting the use of glycated albumin and fructosamine as potential markers of glycemic control, it would be reasonable to use HbA1c as the reference standard for hemodialysis patients with diabetes." (PMID 26645204, 2015). "Our findings suggest that CKD patients with diabetes had lower serum albumin and a higher proportion of hypomagnesemia, and this may be related to the development of osteoporosis." (PMID 26273297, 2015). "Multiple stepwise regression analysis was performed using ΔERI as the dependent variable and clinical parameters including age, sex, HD duration, the presence of diabetes, serum albumin, Hb concentrations, and mineral and iron parameters as independent variables." (PMID 25988769, 2015). "Interaction was observed between albumin and diabetes and between phosphorus and albumin." (PMID 26121574, 2015). "PCPs were more likely to refer patients with diabetes in the stage 3 subgroup, which may reflect a higher rate of urine albumin screening and appropriate subsequent referral of albuminuric patients." (PMID 26458541, 2015). "Although the relationship between BNP and microalbuminuria levels remains unclear in patients with diabetes mellitus, the infusion of atrial natriuretic peptide increases the urinary excretion of albumin in patients with diabetes mellitus." (PMID 26473035, 2015). "The first clinical sign suggesting renal involvement due to diabetes is hyperfiltration characterized by increased glomerular filtration rate over 120 mL/min/1.73 m2, which is followed by the onset of microalbuminuria (albumin excretion >30 mg/g creatinine)." (PMID 26239461, 2015). "We subsequently adjusted for SCr, ALB, hypertension, diabetes, smoking and drinking status (influential factors on IgM levels), and any family history of diseases including CVD, hypertension, hyperlipidemia, and diabetes (all of which are recognized as genetic factors for dyslipidemia)." (PMID 25915947, 2015). "After adjusting for group (elderly PD vs. elderly HD), age, hemoglobin, albumin, 24-h urine volume, SGA, diabetes, and hospitalization, the risk of death 0.73 times lower in the elderly PD group than in the elderly HD group, but the difference was not statistically significant (P = 0.380)." (PMID 26121574, 2015). "Inflammation was the only domain predicting survival in all age groups, although it did not remain significant in the centenarians (100–104 years) after additional adjustments for education, history of CVD, hypertension, diabetes, hyperlipidaemia, and low albumin." (PMID 26629551, 2015). "Furthermore, we found that diabetes dramatically induced kidney injury molecule 1 (Kim-1), a marker for proximal tubular injury, and downregulated cubilin, a receptor for albumin uptake." (PMID 26398934, 2015).